EIF2AK2 (eukaryotic translation initiation factor 2 alpha kinase 2)
Diseases named in the same sentence as EIF2AK2 in open-access papers (continued):
Sharing a sentence is not in itself a finding about the gene and the disease.
tumor (173 papers, 2007 to 2026). "GSDME activation can modulate infiltration of immune cells, including tumor‐associated macrophages (TAMs), through EIF2AK2, significantly improving anti‐tumor immunotherapy." (PMID 40783818, 2025). "Among them, INHBA, HSP90AA1, and EIF2AK2 were significantly higher expressed in tumor samples than in normal samples." (PMID 39006030, 2024). "To explore the possible reasons for increased PRKRA expression and poor prognosis in HBV-related HCC, we compared the mRNA expression of EIF2AK2 in tumor tissues and blood samples from the HBV-related HCC patients." (PMID 35729579, 2022). "Similar to the expression pattern of PRKRA, EIF2AK2 was also upregulated both in tumor tissues and peripheral blood samples." (PMID 35729579, 2022). "In addition, EIF2AK2 (often also referred to as PKR) is a double‐stranded RNA‐activated protein kinase, which has additionally been reported to suppress tumour growth, which was upregulated after LRP downregulation." (PMID 36579897, 2023). "The network indicated that hsa-miR-6799-5p and hsa-miR-6759-5p, two tumor suppressor-related miRNAs, could interact with EIF2AK2 and IFI44L simultaneously." (PMID 35495164, 2022). "We found that EIF2AK2 exhibited sexually dimorphic prognosis of GBM in TCGA and CGGA, consistent with both its anti- and pro-tumor effects." (PMID 35406793, 2022). "Three activated UPRs associated with immune activation were unique to CPA/6d-treated GL261(B6) tumors: EIF2AK2, IFNL1 and MAVS, while the two activated UPRs specific to GL261(scid) tumor responses, DMD and SPARC, have glial cell-related functions:." (PMID 27515027, 2016). "The data identified several kinases that are up-regulated in tumor cells, including; MET, PFTK1, BUB1, CKS1B, EIF2AK2, and NEK2." (PMID 22280838, 2012). "G3BP1, EIF2AK2, TRIM25, and ACTA1 were among the top-ranked proteins, and these were closely related to tumor proliferation, metastasis, and invasion, suggesting that seRNA-NPCM may play a crucial role in NPC tumorigenesis and development." (PMID 37479693, 2023). "Furthermore, increased expression of a subset of ISGs, including IFITM1, EIF2AK2, STAT1, and IFI27, has been reported in several types of cancers, and these ISGs have been shown to promote tumor growth and resistance to chemotherapy and radiotherapy." (PMID 26897526, 2016). "Ipilimumab may also rescue tumor-impaired IFN-γ pathways in CD4+ T cells, since a number of genes associated with IFN-γ signals such as STAT1, ISG15, GBp1, and EIF2AK2 were up-regulated by ipilimumab (data not shown)." (PMID 22788688, 2012).
cancer (143 papers, 2007 to 2026). A tumor composed of atypical neoplastic, often pleomorphic cells that invade other tissues. "The picture that emerges is one in which PKR (EIF2AK2) is broadly expressed across different cancer types, individual patients within a defined cancer type show considerably variable (up to 10-fold) levels of PKR expression, PKR is rarely mutated, and 5–10% of patients show overexpression of PKR." (PMID 30686999, 2018). "Particularly, the expression of INHBA, HSP90AA1 and EIF2AK2 in ESCC cancer tissues was significantly higher than that in normal tissues, while the level of LRRK2 and HSPB8 in ESCC tissues was remarkably lower as compared to the normal tissues." (PMID 39006030, 2024). "EIF2AK2 is an interferon-inducible, double-stranded RNA protein kinase and its activation can suppress the metastatic capabilities of several cancer cell types." (PMID 35846349, 2022). "INHBA, HSP90AA1 and EIF2AK2 were overexpressed in cancer tissues and cells of ESCC." (PMID 39006030, 2024). "EIF2AK2 also plays a key role in angiogenesis and apoptosis, both of which are hallmarks of cancer." (PMID 35406793, 2022). "The next question we asked ourselves was, how relevant WNK3 and the other four top inhibited targets (EIF2AK2, p38γ, PAK1, and RPS6KA3) are to cancer." (PMID 35163434, 2022). "Besides the genes encoding ZAPs, we also detected five genes encoding signaling molecules involved in the immune response to cancer, namely TRAF6, EIF2AK2, PIK3CA, APAF1, and POU2F2." (PMID 34844636, 2021).
bacterial infections (13 papers, 2015 to 2024). "To investigate whether PKR played a role in the innate immune response to bacterial infections, we measured expression levels of the EIF2AK2 gene that encodes for PKR following Mtb infection using quantitative real-time PCR (qRT-PCR)." (PMID 33552025, 2020). "In neurons, a key part of the defense against viral and bacterial infections is undertaken by the 551 amino acid protein Protein kinase R (PKR), also known as eukaryotic translation initiation factor 2‐alpha kinase 2 (EIF2AK2)." (PMID 32716602, 2021).
EIF2AK2 also shares sentences with these, for which no sentence is quoted: Obesity (22 papers); Insulin resistance (18); hepatocellular carcinoma (17); colon cancer (16); neurodegenerative disease (16); HIV-1 infection (14); neuroblastoma (10); cognitive decline (9); glioblastoma (9); Huntington disease (9); reovirus infection (9); cholangiocarcinoma (8); osteoarthritis (8); systemic lupus erythematosus (8); colitis (7); diabetes (7); gastric cancer (7); lung carcinoma (7); memory impairment (7); metabolic disorders (7); type 2 diabetes (7); ZIKV infection (7); liver cancer (6); autoimmune disease (5); Autoimmunity (5); co-infection (5); neurological diseases (5); osteosarcoma (5); pancreatic cancer (5); parasitic infection (5).
A further 159 diseases each share a sentence with EIF2AK2 in 5 papers or fewer.